IL6 (interleukin 6)
Diseases named in the same sentence as IL6 in open-access papers (continued):
Sharing a sentence is not in itself a finding about the gene and the disease.
glioma (continued). "Oncostatin M (OSM)-treated human glioma U343 cells were used as model for induction of astrocytic IL-6 expression." (PMID 21801384, 2011). "Analysis of conditioned media revealed, that in our experimental setup only OSM treatment significantly induced the expression of IL-6 in human U343 glioma cells." (PMID 21801384, 2011). "Taking our findings into account, it is most likely that midazolam inhibits IL-1β-induced IL-6 release through the JAK/STAT3 pathway suppression in C6 glioma cells." (PMID 21682888, 2011). "The action point of NADPH oxidase in TNF-α-stimulated IL-6 synthesis in C6 glioma cells was investigated." (PMID 20205746, 2010). "In contrast, mRNA levels for the Th17-inducing cytokine, IL-6, is 67±53% in normal mouse brain and increases in WT-glioma and Rag1−/−-glioma mouse brain (618±316% and 356±67%, respectively)." (PMID 21060663, 2010). "It therefore seems unlikely that NADPH oxidase functions at a point of these kinases in TNF-α-induced IL-6 synthesis in C6 glioma cells." (PMID 20205746, 2010). "We evaluated IL-6 gene amplification in tumours from 53 glioma patients using fluorescence in situ hybridisation." (PMID 17224923, 2007). "To address these issues, we evaluated here IL-6 gene amplification using interphase fluorescence in situ hybridisation (FISH) in 53 gliomas representative of various histological types and malignancy grades." (PMID 17224923, 2007). "The aggressiveness of human gliomas appears to be correlated with the upregulation of interleukin 6 (IL-6) gene." (PMID 11506489, 2001). "Second, application of SP or neurokinin A (NKA) to NK1R+glioma cell lines increased the secretion of interleukin 6 (IL-6) and potentiated IL-6 secretion induced by IL-1β." (PMID 9888463, 1999). "Also, IL‐6 signals were associated with the stimulation of STAT3, which was also crucial for glioma stem cells’ survival." (PMID 41498028, 2025). "As expected, ITE treatment reduced IL6/IL11 in cultured glioma cells." (PMID 40283908, 2025). "Interestingly, our own assessment of the Brain Lower Grade Glioma TCGA PanCancer Atlas dataset highlighted that low expression of TP53I3 and high expression of IL6 and MYC was associated with worse survival in mutant IDH1 tumors but not WT IDH1." (PMID 40188944, 2025). "Moreover, neuron-derived cytokines such as IL-6 and chemokines like CXCL12 have been implicated in promoting glioma proliferation, immune evasion, and stem-like cell recruitment." (PMID 40999491, 2025). "Considering the holistic concept of the glioma microenvironment, other microenvironmental components such as microglia may also be part of the extra source of these effector molecules like IL-6 and CCR2." (PMID 40243478, 2025). "Furthermore, the insulin-like growth factor 1 (IGF-1) has been shown to trigger TLR9 expression in glioma cells through activation of hypoxia-induced factor 1 alpha signaling, which in turn stimulates IL-1β, IL-6, IL 8 as well as CXCR4." (PMID 41157253, 2025). "Furthermore, Glioma cells secrete immunomodulatory cytokines like IL-1β, IL-6, TGF-β, and IL-8 to activate or suppress immune response." (PMID 40927709, 2025). "Notably, previous studies have demonstrated that inhibiting IL-6 signaling directly affects glioma cell proliferation in U87 cells and GBM explant cultures." (PMID 40149846, 2025). "Moreover, we found that R-2HG regulates the glioma microenvironment by decreasing IL-6, CCL2, CXCL10, and MMP-14 in microglia." (PMID 41367876, 2025). "Glioma cells produce various immunomodulatory factors, such as IL-1β, IL-6, TGF-β, and IL-8." (PMID 40927709, 2025). "On the other hand, the activation of signaling pathways such as NFκB by TNF by microglia, astrocytes, or glioma cells themselves can induce an increase in IL6 expression, which can activate the JAK/STAT3 pathway and contribute to tumor proliferation, migration, and invasion." (PMID 38248305, 2024). "After blocking TREM1, glioma-derived TAMs expressed less levels of IL-6, IL-8, CCL2 and CCL8." (PMID 38370418, 2024).
glioma (continued). "In addition, the immunoinducible cytokines interferon-γ (IFN-γ) and interleukin-6 (IL-6) can also induce the expression of PD-L1 in the glioma microenvironment." (PMID 39334448, 2024). "The antitumor effect of this molecule can also be observed in an indirect coculture model (via glioma conditioning medium), inducing microglial regulation to a pro-inflammatory profile by increasing the expression levels of cytokines such as IL-1β, IL-6, and IL-18." (PMID 38248305, 2024). "•Blockade of interleukin-6 results in prolonged survival in mouse models of gliomas." (PMID 39512605, 2024). "IL-6, one of the main cytokines involved in Th17 differentiation, can be secreted by resident microglial cells, GBM-associated endothelial cells in the vascular niche, and glioma cells." (PMID 38918274, 2024). "Additionally, in in vitro co-cultures, glioma-derived IL-6 and IL-8 were shown to extend neutrophil survival, suggesting glioma–neutrophil interactions." (PMID 38254796, 2024). "The same glioma cells are known to increase oxidative stress and stimulate the release of immunosuppressive molecules such as interleukin-6 (IL-6), IL-10 and tumor growth factor beta (TGF-β), which in turn reprogram the immune components of TME such as microglia to a pro-tumorigenic phenotype." (PMID 38515789, 2024). "To evaluate the combined impact of the developing glioma and SorLA loss from host cells on the tumor microenvironment, we first assayed the levels of selected cytokines (TNFα, MIP2, CCL5, CXCL1, IL1β, IL2, IL6, and IL10) in the tissue lysates derived from tumor-bearing and tumor-free hemispheres." (PMID 38499808, 2024). "Having determined that glioma-derived M-CSF and IL-34 drive M-MDSC differentiation and GM-CSF and IL-6 are present in the glioma microenvironment, whole bone marrow was harvested, and cells were cultured in the presence of glioma-conditioned media and exogenous GM-CSF and IL-6." (PMID 39272914, 2024). "CCL2, referred to as MCP-1 (Monocyte chemotactic protein-1), is secreted by glioma cells and binds to CCR2 expressed on microglia, inducing microglia to recruit to the glioma region and release interleukin-6 (IL-6) thereby promoting the invasion and growth of glioma cells." (PMID 37700840, 2023). "Subsequently, astrocyte-derived IL-6 acted on glioma cells, leading to further STAT3 activation." (PMID 36923251, 2023). "In Nano-DOX-BMDM-treated mice, Nano-DOX can be delivered to GBM via GBM-associated immune cells (e.g., macrophages) to inhibit STAT3 activation in glioma cells and reduce their export of IL-6 to astrocytes, thereby abolishing feedback activation of astrocytes to glioma cells." (PMID 36923251, 2023). "Glioma-derived factors, such as IL-1β, IL-6, IL-8, and TNFα, are crucial inflammatory mediators that trigger the inflammatory cycle in GBM and also promote carcinogenesis by avoiding growth suppression and apoptosis, inducing angiogenesis and metastasis and maintaining cancer cell stemness." (PMID 38003396, 2023). "Moreover, TAMs seen in gliomas generate and secrete IL-6, which has the ability to stimulate the growth of glioma stem cells and trigger the build-up of TAMs in a feed-forward loop." (PMID 38249077, 2023). "Studies have shown that IL-6 can promote the migration of glioma cells, and cucuritin-1, a specific inhibitor of STAT3, can inhibit this promoting effect of IL-6, suggesting that IL-6 may regulate the invasion of glioma through JAK/STAT pathway." (PMID 38259287, 2023). "Previous studies have indicated that IL-6 promotes glioma cell proliferation." (PMID 37734869, 2023). "Our results further confirmed the key role of IL6 in glioma progression." (PMID 37407973, 2023). "It was reported that IL6 played an important role in glioma." (PMID 37407973, 2023). "Moreover, TANK indirectly phosphorylates the transcription factor STAT3 to increase the release of interleukin-6 (IL-6) and ultimately accelerate the progression of glioma in terms of enhanced angiogenesis and proliferation." (PMID 37215097, 2023).
glioma (continued). "Collectively, our results confirmed that IGF2BP3/circGNB1/miR-515-5p/miR-582-3p/XPR1 axis could promote tumorigenesis and malignant progression of glioma via IL6/JAK2/STAT3 signaling pathway." (PMID 37407973, 2023). "IL-6 is highly expressed in human glioma specimens and cell lines, and activates the transcription of multiple tumor suppressor genes through STAT3 (signal transducer and activator of transcription 3) signaling pathway to promote the proliferation and inhibit apoptosis of U251 and A172 cell lines." (PMID 38259287, 2023). "It was shown that there was a cross-activation of IL6/STAT3 between glioma cells and astrocytes." (PMID 36923251, 2023). "Furthermore, glioma-derived cytokines IL-1β, IL-6, and TNFα were observed to extend neutrophils lifespan from 7 h in normal conditions to 17 h in cancer, which in turn increases the number of neutrophils in peripheral blood." (PMID 38003396, 2023). "In addition, C6 glioma cells had a low tumor migration and viability due to the marked reduction in IL-6 levels when incubated with a conditioned medium of microglia treated with apigenin." (PMID 37375698, 2023). "The pathways enrichment analysis indicated TMSB10 was positively associated with IL6/JAK/STAT3 signaling pathway, and we also found TMSB10 was positively associated with IL-6 in patients with primary/recurrent glioma (grade III: r=0.46, P<0.001, grade IV: r=0.317, P=0.003)." (PMID 37275863, 2023). "Additionally, we revealed that high CENP-A expression phenotype was strongly associated with the inflammation-related IL6-JAK-STAT3 signaling pathway, which is associated with poor prognosis in patients with glioma." (PMID 36105094, 2022). "To understand the molecular mechanisms underlying TMEM158-induced proliferation, migration, and invasion of glioma cells, we examined TMEM158-associated genes, which were enriched in the IL6-JAK-STAT3 signaling pathway as assessed using HALLMARK gene set enrichment analysis." (PMID 34992215, 2022). "TAMs could produce pro-inflammatory mediators including TNF-α, IL-6, and IL-12 to amplify inflammation in gliomas." (PMID 36468012, 2022). "Thus, before initiating treatment, high levels of IL-6, IL-8, IL-17, IL-33, TNF-α, TGF-β, and CRP in the circulation are strongly associated with increased glioma stem cell activity that potentially leads to glioma progression and greater invasiveness." (PMID 35054779, 2022). "Glioma cells try to avoid the attack by the immune system by shutting down the antigen-presenting cells’ (APCs) activity of microglia, an effect mediated by IL-6." (PMID 35053377, 2022). "In GBM (as detected by IHC), tumor cells themselves and peritumoral immune cells can release IL-6, increasing its circulating levels and suggesting that IL-6 may participate in glioma evolution in autocrine or paracrine ways." (PMID 35054779, 2022). "Interleukin 6 (IL6) signaling contributes to glioma aggressiveness." (PMID 36429083, 2022). "Meanwhile, inhibition of glioma IL6 in vivo prolonged mouse survival time." (PMID 36248827, 2022). "Furthermore, H-GDES containing high levels of IL6 and miR-155-3p can induce M2-like macrophage polarization via the IL6-pSTAT3-miR-155-3p-autophagy-pSTAT3 positive feedback loop, thereby promoting the glioma progression." (PMID 36275720, 2022). "IL-6 is known to promote glioma cell proliferation and invasion." (PMID 35720420, 2022). "Interestingly, high expression levels of IL‐6 and IL‐6R have been associated with aggressive subtypes of glioma (i.e. mesenchymal subtype and IDH wild‐type glioma)." (PMID 35029050, 2022). "Phosphorylation of STAT3 and JAK2 was significantly enhanced in glioma cells, and inhibition of IL-6/JAK2/STAT3 signaling pathway could significantly inhibit the proliferation of glioma cells and promote cell apoptosis." (PMID 36591515, 2022).
glioma (continued). "On the contrary, the MeHg exposure with the highest concentration (5 μM-MeHg) used in this study induced a low IL-6 production level measured in C6 glioma cells, while an intermediate concentration (2.5 μM) MeHg provoked an increase in IL-6 levels, on treated cells for 8 h and 16 h." (PMID 36408241, 2022). "This reduction in glioma-derived IL-6, together with altered TLR2 signaling, could concomitantly hinder microglial MMP9 production." (PMID 35992852, 2022). "Indeed, IL-6 expression inhibition in glioma cells and COX2 inhibition in GBM cells abolish the impact of macrophages on vascular mimicry formation by these cells." (PMID 33783686, 2021). "Since NF‐κB facilitates the synthesis of proangiogenic factors including IL‐6 and IL‐8, ROS could promote glioma angiogenesis." (PMID 33300633, 2021). "Moreover, overall survival was lower in patients with high expression of both TGF-β and IL6 than in those with low expression of TGF-β and IL6 in their glioma samples and in the TCGA database." (PMID 33576874, 2021). "Furthermore, TAMs present in gliomas produce and release IL-6, which can increase the formation of glioma stem cells and induce the accumulation of TAMs in a feed-forward cycle." (PMID 34948224, 2021). "Our findings suggest that IL-6 and miR-155-3p may be novel biomarkers for diagnosing glioma and that treatments targeting autophagy and the STAT3 pathway may contribute to antitumor immunotherapy." (PMID 33828078, 2021). "Likewise, TNFα also induces IL-6 production in a variety of cells, such as glioma cells, osteoblasts, and vascular smooth muscle cells, through distinct transduction pathways." (PMID 34831450, 2021). "Mechanistically, TMEM44-AS1 could transcriptionally regulate Myc and EGR1/IL-6 signaling in glioma cells." (PMID 34696771, 2021). "We next examined the molecular mechanisms by which IL6 promotes glioma cancer stemness." (PMID 33576874, 2021). "In addition, the co-implantation of glioma cells and IL-6 or miR-155-3p-overexpressing macrophages resulted in a worse survival time." (PMID 33828078, 2021). "Moreover, the macrophages and glioma cells were co-implanted into nude mice to establish orthotopic xenografts, which were used to investigate the effects of IL-6 and miR-155-3p on macrophages." (PMID 33828078, 2021). "For example, NFAT1-regulated IL6 signaling contributes to the aggressive phenotypes of glioma." (PMID 33768003, 2021). "At present, radiotherapy is one of the main methods to treat glioma, but it leads to an obvious increase in inflammatory factors in the tumour microenvironment, especially IL‐6 and CXCL1, which plays a role in tumour to resistance radiotherapy and tumorigenesis." (PMID 34216174, 2021). "Therefore, the results demonstrated that macrophages overexpressing IL-6 or miR-155-3p promote glioma progression in vivo." (PMID 33828078, 2021). "Our findings also show that IL-6 and miR-155-3p may be novel biomarkers for diagnosing glioma and that treatment targeting autophagy and the STAT3 pathway may impair the immunosuppressive tumor microenvironment and participate in antitumor immunotherapy." (PMID 33828078, 2021). "Furthermore, we confirmed that the overexpression of IL-6 and miR-155-3p in TAMs promotes glioma progression in vitro and in vivo." (PMID 33828078, 2021). "The CD133+ proportion of glioma cells was elevated in the IL6 recombinant protein treatment." (PMID 33576874, 2021). "Moreover, FOXS1 expression in glioma cells was increased by secretion of IL-6 mainly from the CD90low gaMSC subpopulation." (PMID 34256854, 2021). "The results showed that IL-6 and miR-155-3p could promote autophagy in TAMs, which indicated that IL-6 and miR-155-3p delivered by exosomes promote autophagy in TAMs in addition to glioma cells." (PMID 33828078, 2021). "Moreover, IL-6+IL-10+ NKTs exhibit a weak ability to induce apoptosis in glioma cells but have an immunosuppressive effect on CD8 T cell activity." (PMID 34603399, 2021).
glioma (continued). "Also, silencing MMP-2 in glioma cell lines impaired α5, β1 integrin, IL-6 signaling, and STAT3 phosphorylation, thus hindering the proliferation and growth of glioma." (PMID 33854965, 2021). "Similarly, we observed that the phosphorylation of STAT3 (p-STAT3) was activated in the IL6 recombinant protein treatment in glioma cells." (PMID 33576874, 2021). "In our study, we found that IL-6 in gaMSCs could increase the expression of FOXS1 in glioma cells, while the addition of an IL-6 neutralizing antibody could reverse this effect." (PMID 34256854, 2021). "The C6 glioma cell line forms a high percentage of cancer stem-like cells, leading us to speculate whether IL-6 signaling could modulate the differentiation of tumorigenic C6 glioma cells." (PMID 33227992, 2020). "The results revealed that TNF-α/IL-6/sIL-6R could efficiently upregulate the expression of Il-6 more than IL-6/sIL-6R or IL-6 alone in glioma cells." (PMID 33227992, 2020). "Finally, the tumorigenicity of glioma cells was evaluated after treatment with IL-6 signaling inducers." (PMID 33227992, 2020). "RT-PCR results showed that the level of Il-6 mRNA in U373-MG glioma cells was elevated approximately 1-, 2-, and 10-fold by IL-6, a combination of IL-6 and soluble IL-6 receptor (IL-6/sIL-6R), and TNF-α plus IL-6 and soluble IL-6 receptor (TNF-α/IL-6/sIL-6R), respectively." (PMID 33227992, 2020). "The results of sphere formation assays showed that 31.7 ± 7.6% (mean ± SD, n = 3) of glioma cells still could form >40 um spheres after TNF-α/IL-6/sIL-6R treatment." (PMID 33227992, 2020). "Similarly, infection of astrocytoma cells by EV-A71 and CVA9 induced production of VCAM-1, IL-6 and IL-8, while IL-6 and IL-8 were upregulated in EV-A71 infected mouse primary astrocytes and human glioma cells." (PMID 32328043, 2020). "Moreover, recent research indicated that mast cells (MCs) upon activation by glioma cells produce soluble factors including IL-6, which are documented to be involved in cancer-related activities and promoted glioma cell differentiation and growth." (PMID 33324446, 2020). "Since IL-6 produced by glioma cells promotes PD-L1 expression of MDSCs, the immunosuppressive function of MDSC is suppressed by IL-6 KO or an anti-IL-6 antibody and the antitumor effect on glioma cells is enhanced by combination therapy using anti-PD-1 antibodies." (PMID 32707672, 2020). "Herein, we confirmed that increased IL-6 signaling could induce tumorigenic C6 glioma cells to undergo differentiation by assessing changes in biomarker levels, the rate of cell proliferation, and tumorigenicity." (PMID 33227992, 2020). "We observed that a higher dose of IL-6 signaling could effectively induce the differentiation of C6 glioma cells." (PMID 33227992, 2020). "Based on these findings, we speculated that IL-6 signaling likely induces the differentiation of tumorigenic C6 glioma cells to reduce their tumorigenicity." (PMID 33227992, 2020). "We also explored the association between IL-6 and YKL-40 with WHO tumor grade in gliomas WHO grade II-IV, the association between CHI3L1 rs4950928 SNP genotype and plasma YKL-40 levels and differences in plasma IL-6 and YKL-40 levels between patients with newly diagnosed and recurrent GBM." (PMID 32363159, 2020). "Therefore, we demonstrated that TNF-α/IL-6/sIL-6R can differentiate C6 glioma cells more efficiently than IL-6/sIL-6R and IL-6 alone." (PMID 33227992, 2020). "Moreover, TNF-α/IL-6/sIL-6R also decreased the total cell population and the tumorigenicity of glioma cells." (PMID 33227992, 2020). "The TNF-α/IL-6/sIL-6R complex could more efficiently induce the expression of Il-6 than IL-6/sIL-6R or IL-6 alone in a tumorigenic C6 glioma cell line." (PMID 33227992, 2020). "Additionally, the total cell population and the tumorigenicity of glioma cells were all considerably reduced after TNF-α/IL-6/sIL-6R treatment." (PMID 33227992, 2020).